HMGB1 (high mobility group box 1)
Diseases named in the same sentence as HMGB1 in open-access papers (continued):
Sharing a sentence is not in itself a finding about the gene and the disease.
viral infection (continued). "Collectively, these data indicated that in a host with impaired with antiviral immunity (i.e. IRF7-/- mice), IL-33 and HMGB1 contribute to increased ILC2 numbers, type-2 cytokine production and the development of ASM remodelling in response to an early-life viral infection." (PMID 32658914, 2020). "We previously reported that influenza California pandemic H1N1 (pH1N1) virus infection induced serum HMGB1 levels in cotton rats at days 4 and 6 p.i.; however, we did not monitor the kinetics of HMGB1 induced by other influenza A strains." (PMID 29535197, 2018). "The resulting increase in viral load in the airway epithelium led to the release of HMGB1, which via the activation of TLR4 was instrumental in driving ASM remodelling during an early life viral infection, as well as the development of mucus hypersecretion and airway hyperreactivity in later life." (PMID 28099113, 2017). "In this context, not only the IFN system pathway and the immune response pathways were the most significant, but the high mobility group box 1 (HMB1) was also up-regulated in patients before treatment, which signals heightened innate immune responses to virus infection." (PMID 26056580, 2014). "HMGB1 binds tightly to chromatin during some forms of apoptosis, but this phenomenon has never been documented during viral infection." (PMID 21283827, 2011). "However, no strong paradigm of its intracellular role during viral infections has been established, and previous studies demonstrated that HMGB1 can serve as either antagonist or protagonist for viruses." (PMID 35679251, 2022). "Moreover, the highlighted staining of HMGB1 foci induced by virus infection were not readily observed after iCRT14 treatment." (PMID 34008469, 2021). "Interestingly, we found that iCRT14 promotes the release of HMGB1 protein in a context either with or without virus infection." (PMID 34008469, 2021). "However, while the involvement of HMGB1 in a variety of viral diseases has been confirmed, the presence or absence of HMGB1 in ducks and the best approaches to regulate the host’s antiviral innate immune mechanisms are currently unclear." (PMID 32070432, 2020). "Notably, abundant HMGB1 amounts (>2000 pg/mL) were detected, irrespective of virus infection, in SeAx culture supernatants, in agreement with the clinical finding that this signaling molecule may be involved in CTCL progression." (PMID 39123440, 2024). "Blocking IL-13 failed to reduce viral infection of AECs, ASM mass, or cytoplasmic HMGB1 levels in AECs." (PMID 28099113, 2017). "In the case of porcine reproductive and respiratory syndrome virus, recombinant HMGB1 does not affect virus replication in MARC-145 and PAM cells, suggesting virus infection blocked by HMGB1 might be virus-dependent." (PMID 27634894, 2016).
liver fibrosis (69 papers, 2011 to 2025). "HSCs can be activated by HMGB1 which induces autophagy and is implicated in the development of liver fibrosis." (PMID 38069199, 2023). "Experimental and clinical studies have found that the high-mobility group box-1 (HMGB1), recently discovered damage-associated molecular patterns (DAMPs), is substantially enriched in patients with hepatic fibrosis." (PMID 33790974, 2021). "HMGB1 is a late inflammatory mediator that plays an important role in the pathogenesis of many chronic inflammations, which is the main cause of liver fibrosis." (PMID 33790974, 2021). "Recently, emerging studies have indicated that HMGB1 is closely associated with fibrotic disorders, including liver fibrosis." (PMID 30258438, 2018). "Originally described as a nuclear protein, emerging studies have showed that HMGB1 is closely associated with fibrotic disorders, including liver fibrosis." (PMID 30546364, 2018). "This was further supported in a study highlighting a significantly increased level of HMGB1 in patients with liver fibrosis caused by hepatitis B." (PMID 30546364, 2018). "Interestingly, elevated HMGB1 expression is linked to various liver diseases, including hepatitis B, liver fibrosis, and liver cancer." (PMID 40579434, 2025). "Together these data support the possibility of HMGB1 as a mediator of fibrogenesis in the liver, and the potential for HMGB1 to be investigated as a predictive biomarker to identify individuals who may be at risk for liver fibrosis progression." (PMID 38518655, 2024). "In addition, HMGB1 is linked to autophagy induction, promoting the activation of hematopoietic stem cells and liver fibrosis." (PMID 38034869, 2023). "HMGB1 belongs to the family of damage-associated molecular patterns (DAMPs) and elevated serum and liver HMGB1 and other DAMPs levels have been widely reported in liver fibrosis and cirrhosis." (PMID 28535799, 2017). "Therefore, CA-induced protection against liver fibrosis is associated with the HMGB1/TLR4/NF-κB pathway." (PMID 29403377, 2017). "Furthermore, it has been demonstrated that HMGB1 could directly activate HSCs by controlling HSC autophagy in liver fibrosis development models linked to the hepatitis B virus (HBV)." (PMID 37298621, 2023). "In addition, circulating HMGB1 level also correlates with the severity of inflammation and hepatic fibrosis associated with NAFLD, and inhibition of HMGB1 release from hepatocytes, or treatment with neutralizing antibodies to HMGB1, attenuates liver damage during NAFLD." (PMID 33238880, 2020). "Therefore, we hypothesized that miRNAs might be associated with the regulation of HMGB1 in BDL-induced liver fibrosis." (PMID 29403377, 2017). "We have previously reported that the HMGB1 peptide, synthesized from box A of the HMGB1 protein, ameliorates liver fibrosis and is a promising candidate for fibrosis-improving drugs against liver cirrhosis." (PMID 40503100, 2025). "Existing evidence indicates that inhibiting HMGB1 significantly reduces the inflammatory response and liver fibrosis." (PMID 41154556, 2025). "Phenolic acids can also inhibit the development of liver fibrosis by acting on the HMGB1/TLR4/NF-κB pathway." (PMID 41154556, 2025). "Regarding hepatoprotection, ICGA-A mitigates CCl4-induced hepatic fibrosis by inhibiting the high-mobility group box 1 (HMGB1)/TLR4/NF-κB signaling pathway." (PMID 41142236, 2025). "HMGB1 inhibitors significantly inhibit the progression of liver fibrosis, indicating that HMGB1 plays an important role in liver fibrosis." (PMID 38105713, 2024). "Studies have highlighted the significant role of HMGB1, a potent mediator, in various fibrotic diseases such as liver fibrosis, renal fibrosis, and pulmonary fibrosis." (PMID 39331598, 2024). "Targeted elimination of HMGB1 specifically in hepatocytes partly prevented CCL4- induced hepatic fibrosis." (PMID 39008169, 2024).
liver fibrosis (continued). "HMGB1 promotes the proliferation and activation of HSCs to promote liver fibrosis during disease progression, and the high level of HMGB1 at the injury site recruits fibroblasts, endothelial cells and smooth muscle cells to repair tissue damage." (PMID 38105713, 2024). "TGFB1 was involved in four upregulated signaling pathways including hepatic fibrosis, HMGB1, macrophage classical activation, and wound healing." (PMID 39660530, 2024). "Silymarin improves CCl4-induced liver fibrosis through enhancing of Egr1 accumulation in nucleus, decreasing serum HMGB1 levels, and inhibiting hepatic EndoMT in mice." (PMID 39008169, 2024). "A study has revealed that in liver fibrosis triggered by CCl4 in mice, HMGB1 expression is induced in the liver." (PMID 39008169, 2024). "DAMPs, e.g., HMGB1, link cell death mechanism autophagy with the onset of liver diseases, e.g., liver fibrosis." (PMID 38069199, 2023). "HMGB1 is associated with NAFLD, alcoholic liver disease (ALD), liver I/R, hepatocyte carcinoma, and liver fibrosis." (PMID 38069199, 2023). "In fibrotic liver disease, HMGB1 is significantly elevated and plays a central role in hepatic fibrosis." (PMID 38034869, 2023). "Several studies have been undertaken to evaluate HMGB1 as a biomarker in plasma of CLD patients to monitor liver fibrosis." (PMID 37048161, 2023). "In multiple experimental models of murine liver fibrosis associated with cholestasis, alcoholic steatohepatitis or NASH increased expression and release of HMGB1 are induced." (PMID 38002056, 2023). "ExosiRNA−OPN was found to inhibit TGF-β1 signaling by reducing HMGB1, then to attenuate the progression of liver fibrosis in a CCl4-induced mouse model of liver fibrosis." (PMID 37298621, 2023). "Our research demonstrated that HMGB1-produced DNA gaps effectively cured conditions such as senile dementia, poor liver function, liver fibrosis, and reversed symptoms of insulin resistance, increased visceral fat, and the size of islets of Langerhans33." (PMID 37923892, 2023). "It is suggested that ICQA protects against liver fibrosis induced by CCl4 by inhibiting the HMGB1/TLR4/NF-κB signaling pathway." (PMID 38202710, 2023). "The release of HMGB1 from damaged cells triggers a cascade of inflammatory cytokine/chemokine events, which further aggravates organ damage and accelerates liver fibrosis." (PMID 36999514, 2023). "Recently, increasing evidence has suggested a role for HMGB1 derived from necroptotic hepatocytes in promoting liver fibrosis and inhibiting the necroptotic pathway-attenuated HMGB1 cytoplasmic translocation and liver damage." (PMID 36110858, 2022). "In NAFLD patients and mouse models, liver fibrosis can be treated by the mineralocorticoid receptor (MR)/osteopontin (OPN)/HMGB1 axis." (PMID 36267567, 2022). "In a mouse model of carbon tetrachloride-induced liver fibrosis, the increase in serum HMGB1 was proportional to the elevation of TGF-β1 and collagen deposition during fibrogenesis." (PMID 35335612, 2022). "The α-SMA and high-mobility group box-1 (HMGB-1), another important driver of liver fibrosis 55, were significantly increased by HFD in WT and Fndc5-/- mice liver tissues." (PMID 33754067, 2021). "To prove the effect of HMGB1 in liver fibrosis, we knocked down the expression of HMGB1 in the liver of mice by adenovirus interference." (PMID 35046917, 2021). "There is evidence that HMGB1 can directly stimulate hepatic stellate cells (HSCs) activation to accelerate the development of liver fibrosis." (PMID 33790974, 2021). "Taken together, our data reveal that AR significantly inhibits liver fibrosis by intervening in the HMGB1-mediated inflammatory signaling pathway and secretion signaling pathway." (PMID 33790974, 2021). "Literature research found that HMGB1, a cytokine abundantly enriched in patients with liver fibrosis, mediated TLR4//NF-κB signaling pathway is one of the important pathways for liver aseptic inflammation." (PMID 33790974, 2021).
liver fibrosis (continued). "As several studies suggested a direct effect of HMGB1 on hepatic stellate cells (HSCs) in the development of liver fibrosis, we sought to further study the role macrophage derived‐HMGB1." (PMID 32123829, 2019). "Previous researches reported that HMGB1 was closely involved in fibrotic disorders including cystic fibrosis, liver fibrosis, and pulmonary fibrosis." (PMID 31933629, 2019). "When using this list for an Ingenuity Pathway Analysis (IPA), “HMGB1 pathway” (p = 9.26 × 10−10) followed by “Hepatic fibrosis/Stellate cell activation” (2.68 × 10−09) was suggested as the two top canonical pathways associated with the RETN polymorphism." (PMID 31645609, 2019). "In support of this observation, neutralization of HMGB1 protected, whereas injection of recombinant HMGB1 promoted, liver fibrosis." (PMID 31731454, 2019). "Using two models of chemically (CCL4) or surgically (BDL)‐induced liver fibrosis, we show that HMGB1 protein levels were strongly upregulated in fibrotic livers compared to control livers suggesting a possible role of HMGB1 during fibrogenesis." (PMID 32123829, 2019). "Curcumin is effective in preventing liver fibrosis, partly due to downregulation of HMGB1, TLR2, and TLR4 via the inhibition of pro-inflammatory mediators and HSC activation." (PMID 30258438, 2018). "Since GZR- or DIC-mediated inhibition of HMGB1 culminated in the downregulation of IL-13, a cytokine known to be involved in liver fibrosis regulation, we decided to investigate the role of HMGB1 in the pro-fibrotic processes of murine schistosomiasis." (PMID 30258438, 2018). "HMGB1 serum levels are significantly increased in patients with liver fibrosis, which is a non-invasive, repeatable, and convenient marker of infection with the hepatitis B virus." (PMID 30258438, 2018). "In this regard, HMGB1 was localized in the cytoplasm of hepatocytes in models of hepatic fibrosis induced by concanavalin A or carbon tetrachloride." (PMID 30258438, 2018). "HMGB1 is an important inflammatory response mediator, and HMGB1/toll-like receptors (TLRs) have been shown to play critical roles in liver inflammation and liver fibrosis." (PMID 29403377, 2017). "A growing number of investigations have implicated a role for HMGB1 in fibrotic diseases, with increased levels of HMGB1 in patients that have systemic sclerosis, cystic fibrosis, liver fibrosis, or pulmonary fibrosis." (PMID 26247017, 2015). "Recently, emerging studies indicate that HMGB1 is closely involved in fibrotic disorders including cystic fibrosis, liver fibrosis and pulmonary fibrosis, while HMGB1 signal inhibitions protect against the experimental models of fibrotic diseases." (PMID 25284457, 2014). "Injection of an HMGB1 neutralizing antibody or recombinant HMGB1 may either decrease or promote liver fibrosis respectively." (PMID 39008169, 2024). "We showed that higher serum levels of high mobility group box 1 (HMGB1), a damage associated molecular protein which increases with cellular apoptosis, at the time of enrolment and lower CD4+ T cell nadir (%) was associated with liver fibrosis progression." (PMID 38518655, 2024). "Hepatocytes are the primary origin of HMGB1 in liver fibrosis induced by CCl4." (PMID 39008169, 2024). "Notably, neutralization of HMGB1 protected against liver fibrosis, whereas injection of recombinant HMGB1 promoted liver fibrosis." (PMID 38002056, 2023). "We and others have demonstrated that extracellular HMGB1 may serve as an alarmin signal to activate macrophage inflammatory responses, and a key driver of inflammasome activation and liver fibrosis." (PMID 37122751, 2023). "In addition to chlorogenic acid, isochronogenic acid A (ICQA) reduces liver fibrosis and the expression of high-mobility group box 1 (HMGB1) and TLR4, alleviates NF-κB p65 nuclear translocation, and inhibits p-IKB expression." (PMID 38202710, 2023).
liver fibrosis (continued). "Based on these data, inhibiting extracellular HMGB1 activity or preventing its release may be beneficial therapeutic targets in treating cholestasis-induced liver fibrosis." (PMID 37454204, 2023). "Therefore, the current study goal was to elucidate the potential anti-fibrotic effects of diacerein on BDL-induced liver fibrosis and the probable related mechanism, with emphasis on HMGB1/RAGE pathway." (PMID 37454204, 2023). "Coincidently, OPN was identified to be the upstream of HMGB1 involved in liver fibrosis, which is accordance with our previous finding that OPN could induce HMGB1 in HSCs activation." (PMID 36120332, 2022). "HMGB1 inhibitors significantly inhibit SSLF, which indicates that HMGB1 plays a role in promoting liver fibrosis, though its mechanism is unknown." (PMID 36389166, 2022). "Moreover, recent studies suggest that HMGB1 is significantly upregulated in patients with schistosome-induced hepatic fibrosis as well as animal models." (PMID 35335612, 2022). "However, this decompensation repair has resulted in liver fibrosis due to persistent inflammation and injuries, and HMGB1 promotes the migration of immune cells to the area of egg granulomas." (PMID 36389166, 2022). "Therefore, we assumed that iExosomes containing siRNAOPN inhibited TGF-β1 expression via inhibiting HMGB1 translocation to cytoplasm and further inactivating HSCs and reducing liver fibrosis." (PMID 36120332, 2022). "Recent research confirmed the role of HMGB1 in liver fibrosis." (PMID 35187072, 2021). "In this study, we also demonstrated that knockdown of HMGB1 expression could alleviate liver fibrosis in BALB/c mice infected with H. hepaticus at 3 and 4 MPI." (PMID 35046917, 2021). "The immunoblot results showed knockdown of HMGB1 could decrease the expression of hepatic α-SMA and collagen I in BALB/c mice infected with H. hepaticus at 4 MPI, suggesting the release of HMGB1 influenced the progression of liver fibrosis." (PMID 35046917, 2021). "We hypothesized that excessive extracellular HMGB1 would aggravate chronic hepatic injury during the development of H. hepaticus–induced liver fibrosis in BALB/c mice." (PMID 35046917, 2021). "Emerging evidences suggested that HMGB1/TLR4/NF-κB signaling was firmly associated with the activation of HSCs as well as the synthesis of ECM, and inhibition of HMGB1 could significantly reduce inflammatory response and ameliorate liver fibrosis." (PMID 32425800, 2020). "Taken together, our study indicated that ICQA could protect against CCl4-induced liver fibrosis probably through suppressing the HMGB1/TLR4/NF-κB signaling pathways." (PMID 32425800, 2020). "Hepatocyte-derived HMGB1 is also involved in liver fibrosis." (PMID 32431618, 2020). "Blocking HMGB1 can partially prevent the consequences of mouse CCL4-induced liver fibrosis." (PMID 32431618, 2020). "Furthermore, SAHA-induced suppression of HSC activation is in part mediated by NF-κB downregulation, which plays a crucial role in liver fibrosis, through the acetylation of high mobility group box 1 (HMGB1)." (PMID 33086678, 2020). "HMGB1 has been shown to be a driving factor of hepatic fibrosis." (PMID 31731454, 2019). "Thus, HMGB1 appears to play a key role in liver fibrosis by activating the HSC via RAGE receptor to stimulate collagen synthesis and deposition in liver fibrosis in the particular rodent models of fibrosis." (PMID 31731454, 2019). "To determine whether macrophage‐derived HMGB1 is playing a key role in fibrogenesis, we first studied liver fibrosis." (PMID 32123829, 2019). "Our results showed that EP could inhibit HSC activation as EP significantly downregulated the HMGB1 level at 4 and 6 weeks of liver fibrosis induced by BDL, while IL-1β and TNF-α levels decreased substantially." (PMID 31933629, 2019). "HMGB1 activates HSCs to stimulate liver fibrosis in the in vitro and in rodent models of fibrosis." (PMID 31731454, 2019).